APOL1 (apolipoprotein L1)
Diseases named in the same sentence as APOL1 in open-access papers (continued):
Sharing a sentence is not in itself a finding about the gene and the disease.
HIV-associated nephropathy (30 papers, 2015 to 2025). Renal disease in human immunodeficiency virus (HIV)-infected patients. "Coding variants in APOL1 are strongly associated with HIV-associated nephropathy (HIVAN) in persons with untreated HIV infection; however, the mechanism by which APOL1 variant protein potentiates renal injury in the presence of high viral load is not resolved." (PMID 30733721, 2019). "APOL1 risk alleles were previously shown to be associated with HIV nephropathy (HIVAN)." (PMID 27933432, 2017). "Previously, carriage of two high-risk APOL1 variants has been strongly associated with HIV-associated nephropathy (HIVAN) with odds ratios ranging from 29 to 89 (in African American and black South African cohorts of 1378 and 228 participants respectively)." (PMID 38360481, 2024). "APOL1 is most strongly associated with HIV-associated nephropathy (HIVAN), with odds ratio (OR) 29 in African Americans and OR 89 in South Africans, suggesting a strong interaction between APOL1 and the HIV-1 virus." (PMID 30733721, 2019). "The discovery of the association of APOL1 genetic variants with FSGS and particularly HIV-associated Nephropathy (HIVAN) (odds ratio 17 and 29 respectively) has led to extensive effort to characterize the potential role of the protein product of APOL1." (PMID 27600725, 2016). "Although HIV-associated nephropathy (HIVAN), especially in individuals carrying APOL1 risk alleles, was once the most common form of kidney injury in PLWH, its incidence has declined dramatically in the current ART era." (PMID 41282841, 2025). "One and a half decades ago, variants (G1 and G2) in the apolipoprotein L1 (APOL1; G0) gene were reported with an excess risk of Focal Segmental Sclerosis (FSGS), HIV-Associated Nephropathy (HIVAN), and other forms of CKD and ESKD in AAAs." (PMID 40001508, 2025). "The classic involvement of the kidney by HIV infection is HIV-associated nephropathy (HIVAN), occurring typically in young adults of African ancestry with advanced HIV disease in association with APOL1 high-risk variants." (PMID 25725239, 2015). "There is limited data to support the use of glucocorticoids in COVAN; however, the mechanism of podocytopathy is similar to that in HIVAN (HIV-associated nephropathy), with high disease burden in those with APOL1 gene mutation." (PMID 37485073, 2023). "Patients of African ancestry with untreated HIV-1 infection and carrying the G1 or G2 kidney disease risk variants (Vs) at the APOL1 gene have a tenfold higher risk of developing HIV-associated nephropathy (HIVAN) compared to those with the non-risk wild type (WT) G0 variant." (PMID 27599995, 2016). "This presentation of FSGS is associated with apolipoprotein L1 (APOL1) risk genotypes and has been labeled COVID-associated nephropathy (COVAN) for its resemblance to another viral-induced FSGS, HIV-associated nephropathy (HIVAN)." (PMID 37927001, 2023). "In addition, APOL1 transgenic mouse models were made proteinuric by intercrossing with a model of HIV-associated nephropathy (HIVAN), a CKD strongly associated with carriage of APOL1 risk alleles, to determine if proteinuria would change the appearance of APOL1 protein in tubular epithelial." (PMID 34138902, 2021). "Another concern is that APOL1 carriers of two risk alleles who developed HIV-associated nephropathy (HIVAN) may not have been enrolled in the seroprevalent cohorts." (PMID 33674766, 2021).
kidney failure (27 papers, 2013 to 2026). An acute or chronic condition that is characterized by the inability of the kidneys to adequately filter the blood. "Second, is the association between one risk allele genotype and kidney failure, at least for the APOL1 G2 risk allele in Bedouins." (PMID 39927257, 2025). "In this study, we prospectively screened a non-selective multiethnic cohort of 1744 Israeli individuals with kidney failure for the presence of APOL1 G1 and G2 variants." (PMID 39927257, 2025). "High-risk APOL1 genotypes were associated with an increased risk of kidney failure (HR = 1.67) and faster eGFR decline (–2.28 vs. 0.25 mL/min/1.73 m2), replicating prior findings." (PMID 39225089, 2024). "By contrast, APOL1 high-risk genotypes were associated with a nearly 3-fold greater risk of kidney failure when other renal pathologies were present." (PMID 35497797, 2022). "Less frequent autoptic findings include micro-angiopathy and collapsing glomerulopathy, a frequent cause of proteinuria rapidly progressing to kidney failure, which predominantly affect patients with homozygous apolipoprotein L1 (APOL-1) high-risk alleles." (PMID 35928822, 2022). "Overall, these results suggest that high-risk APOL1 mice died due to kidney failure or from sequelae of extreme proteinuria." (PMID 34350953, 2021). "Clinical characteristics of patients with kidney failure carrying at least one APOL1 risk variant." (PMID 39927257, 2025). "However, only some individuals with APOL1 high-risk genotypes have CKD or kidney failure, indicating genetic background contributes to the APOL1 high-risk kidney disease relationship." (PMID 40236664, 2025). "Consequently, our aim in this study was to investigate the prevalence of APOL1 risk variants among Israeli patients with kidney failure." (PMID 39927257, 2025). "Furthermore, it confirmed the association between high-risk APOL1 genotypes and kidney failure and eGFR decline." (PMID 39225089, 2024). "A complex combination of bacterial, viral and parasitic infections coupled with a well-documented genetic predisposition, the Apolipoprotein L1 (APOL1) kidney risk variants have sustained the importance of glomerulonephritis as a cause of kidney failure in Africa." (PMID 37869232, 2023). "Hence, we established a large cohort of people of recent African ancestry with HIV in the United Kingdom to study the prevalence of APOL1 risk alleles and their relationship to kidney failure requiring RRT, HIVAN/FSGS, and milder manifestations of CKD." (PMID 35497797, 2022). "To determine whether high-risk APOL1 mice were experiencing kidney failure, we measured markers of kidney and liver function." (PMID 34350953, 2021). "APOL1 has substantial clinical significance for people of recent African ancestry because of two common variants that covey resistance to infection by Trypanosoma brucei rhodesiense, but which later lead to kidney failure." (PMID 31058853, 2019). "Additionally, the apolipoprotein L1 (APOL1) G1 or G2 at-risk alleles for kidney diseases may accelerate progression to kidney failure in patients with LN (Hiraki)." (PMID 36251071, 2023). "Using elastic net Cox regression adjusted for age, sex, eGFR and albuminuria, we derived a nine-protein APOL1 Proteomic Risk Score (APRS) that predicts a composite outcome of ≥40% eGFR decline, kidney failure or death." (PMID 41986737, 2026). "Ongoing efforts to disentangle the impact of social constructs like race from biological factors like APOL1 on progression of kidney failure remain important." (PMID 39729127, 2025). "For instance, variants in the APOL1 gene (common in individuals of African ancestry) significantly increase the risk of CKD and kidney failure." (PMID 40563449, 2025). "In contrast, APOL1 HRG was significantly associated with eGFR, the CKD stage, and kidney failure in adults with any SCD genotype." (PMID 38791464, 2024).
kidney failure (continued). "HIVAN is a collapsing glomerulopathy and a major cause of kidney failure in populations with untreated or under-treated HIV infection, especially in those with APOL1 high-risk genotypes." (PMID 35497797, 2022). "In conclusion, despite AMKD being a rare cause of kidney failure in the Israeli population, APOL1 risk variants, G1 and G2, do exist in populations without explicit recent sub-Saharan ancestry." (PMID 39927257, 2025). "We non-selectively screened people with kidney failure across Israel for APOL1 risk variants using restriction fragment length polymorphism." (PMID 39927257, 2025). "In Columbia-GN and Columbia-CKD, high-risk APOL1 genotypes were associated with an increased risk of kidney failure, while CureGN showed a nonsignificant trend toward increased risk (HR = 1.72, 1.74, and 1.28; P = 0.018, 1.14 × 10–6, and 0.31, respectively)." (PMID 39225089, 2024). "Meta-analysis of the effect of specific high-risk APOL1 genotypes showed an increased risk of kidney failure without heterogeneity between the 3 high-risk APOL1 genotypes, or across the 3 studies (HR = 1.67, P = 9.13 × 10–10)." (PMID 39225089, 2024). "Recent studies give evidence that three coding SNPs on the last exon of APOL1 gene, lying on extended haplotypes with the MYH9 SNPs (haplotypes E1, F1 and S1), may be the actual cause for predisposition to renal failure." (PMID 23516419, 2013). "The outcome of living donors who are homozygous for the APOL1 variant is unknown; however, it is tempting to speculate that much, if not all, of the excess risk of renal failure in African American donors may be attributable to APOL1 risk variant [56•]." (PMID 27004159, 2016). "Although we did not have information on Apolipoprotein L1 (APOL1) risk gene mutation status, the mutation is present in approximately 13% of African Americans in the United States and may have contributed to higher rates of kidney failure in our Black population." (PMID 36718187, 2023). "A previous study in African Americans reported no impact of APOL1 status on the rate of progression to kidney failure requiring RRT in people who had been diagnosed with HIVAN." (PMID 35497797, 2022).
diabetic kidney disease (26 papers, 2011 to 2025). Progressive kidney disorder caused by vascular damage to the glomerular capillaries, in patients with diabetes mellitus. "Certain alleles of the APOL1 gene are associated with increased susceptibility to non-diabetic kidney disease." (PMID 39457715, 2024). "Multiple variants in APOL1, including rs2239785, have been associated in a recessive model with diabetic and non-diabetic nephropathy in African American individuals." (PMID 37585454, 2023). "Individuals with two copies of the apolipoprotein-1 (APOL1) gene risk variants are at high risk (HR) for non-diabetic kidney disease." (PMID 31182139, 2019). "The highest frequencies of renal related variants of apolipoprotein L1 (APOL1)-associated with non-diabetic kidney disease are reported among West Africans." (PMID 30471633, 2019). "Apolipoprotein L1 (APOL1) genetic variants G1 and G2, compared to the common allele G0, are major risk factors for non-diabetic kidney disease in African descent populations." (PMID 30998685, 2019). "This strong association between APOL1 polymorphisms and non-diabetic kidney disease found in studies in this review have been replicated in several studies since the initial findings reported in African Americans." (PMID 30340464, 2018). "APOL1 G1 and G2 risk alleles are common in African Americans and markedly influence susceptibility to non-diabetic kidney disease; furthermore, the two renal-risk-variant genotypes in deceased donors accelerate renal-allograft failure." (PMID 27054572, 2016). "Two coding variants in the apolipoprotein L1 gene (APOL1) are associated with non-diabetic nephropathy and end-stage kidney disease in African Americans." (PMID 27054572, 2016). "In conclusion, our study provides evidence that genetic variants in APOL1 are present in a mixed-ancestry South African population, but their association with renal diseases needs further exploration in patients with non-diabetic kidney diseases." (PMID 26112018, 2015). "The strong association between APOL1 and non-diabetic kidney diseases has been replicated in several studies since the initial observations reported in African Americans with hypertensive kidney disease and FSGS." (PMID 26112018, 2015). "Association of Candidate Diabetic Kidney Disease Loci with T2D-ESKD after Adjustment for APOL1 G1/G2." (PMID 24551085, 2014). "Inheritance of 2 APOL1 risk alleles (G1 and G1, G1 and G2, or G2 and G2) increases the risk of non-diabetic kidney disease by over sevenfold." (PMID 22956460, 2013). "Coding variants in APOL1 are major susceptibility loci for non-diabetic nephropathy; however, independent, weaker MYH9 effects remain plausible." (PMID 21698141, 2011). "Meanwhile, the candidate gene analysis demonstrated a strong association for diabetic neuropathy (MAPK14: rs3761980, rs80028505), and diabetic nephropathy (APOL1: rs136161), proving the contribution of these risk loci in the pathogenesis of diabetic complications across various populations." (PMID 33430853, 2021). "APOL1-associated forms of non-diabetic kidney disease and T2D often co-exist in patients." (PMID 31092297, 2019). "The most significant association with T2D-ESKD (OR = 0.77, P = 1.42 × 10−10) and all-cause ESKD (OR = 0.69, P = 1.96 × 10−25) in the baseline model was an intronic variant rs9622363 in the APOL1 region associated with non-diabetic kidney disease in individuals with African ancestry." (PMID 31092297, 2019). "Apolipoprotein L1 gene (APOL1) G1 and G2 renal-risk variants, common in populations with recent African ancestry, are strongly associated with non-diabetic nephropathy, end-stage kidney disease, and shorter allograft survival in deceased-donor kidneys (autosomal recessive inheritance)." (PMID 27054572, 2016). "However, APOL1-associated non-diabetic kidney disease may be the true cause of kidney disease in many such patients." (PMID 31092297, 2019).
diabetic kidney disease (continued). "Apolipoprotein L1 (APOL1) high-risk genotypes (HRG), G1 and G2, increase the risk of various non-diabetic kidney diseases in the African population." (PMID 34440683, 2021). "By applying the targeted approach we managed to replicate two significant associations for diabetic neuropathy rs3761980 and rs80028505, both mapping to MAPK14 loci and one significant hit (rs136161, APOL1) for diabetic nephropathy in our study cohort." (PMID 33430853, 2021). "By applying the targeted approach of previously reported susceptibility loci we managed to replicate three associations: MAPK14 (rs3761980, rs80028505) and diabetic neuropathy, APOL1 (rs136161) and diabetic nephropathy." (PMID 33430853, 2021). "Overall, these data implicate both MYH9 and APOL1 as significant biological contributors to non-diabetic nephropathy and intimate context-dependent roles in disease pathology." (PMID 26147622, 2015). "Novel therapies, including endothelin receptor antagonists, sodium‐glucose cotransporter‐2 (SGLT2) inhibitors, and APOL1‐targeted therapies, are being explored for their potential to reduce proteinuria and protect against glomerular damage in patients with FSGS and diabetic nephropathy." (PMID 39568532, 2024). "Therefore, we tested for interactions between single nucleotide polymorphisms across the genome with APOL1 and MYH9 non-diabetic nephropathy risk variants in African Americans with presumed diabetic nephropathy." (PMID 21698141, 2011).
viral infection (22 papers, 2018 to 2025). "The CKDs most strongly associated with APOL1 risk variants are triggered by viral infections, such as human immunodeficiency virus-associated nephropathy (HIVAN), coronavirus disease-associated nephropathy (COVAN), and others." (PMID 40940784, 2025). "This emphasizes the relevance of APOL1 genotyping in cases of podocytopathies associated with viral infections." (PMID 41278320, 2025). "The association of APOL1 polymorphism and collapsing glomerulopathy was also previously reported in patients with other viral infections." (PMID 39225763, 2025). "Podocyte and tubular injury due to viral infection or systemic inflammation, with APOL1 genotypes increasing susceptibility." (PMID 41009556, 2025). "Pathological insights are explored and discussed, including mechanisms of HIV-associated renal injury, such as direct viral infection of renal epithelial cells and genetic predispositions linked to Apolipoprotein L1 (APOL1) variants." (PMID 41295583, 2025). "CG presents at more advanced stages and with poorer renal function, which emphasizes that it must be evaluated properly, especially in developing countries where risk factors, such as APOL1 mutations and viral infections, are more common." (PMID 35308512, 2022). "The clinical and pathological similarity with HIVAN and the remarkable relationship between viral infection and high-risk APOL-1 genotype suggests the term COVAN to describe this entity." (PMID 33799854, 2021). "The risk factors associated with this uncommon form of glomerular injury in kidney allografts include, but are not limited to, the donor's high-risk APOL1 genotype, viral infections (such as cytomegalovirus, human immunodeficiency virus, Epstein-Barr virus, SARS-CoV-2, parvovirus, and BK virus)." (PMID 39866980, 2024). "It is well established that interferons induce upregulation of APOL1 gene expression (as well as other APOL family genes), leading to the suggestion that the interferon response to viral infection triggers the development of kidney disease via the upregulation of APOL1 G1 or G2 variants." (PMID 34331942, 2021). "Therefore, it appears that two hits are required to confer podocyte stress: APOL1 variants and another factor or factors, such as interferon or viral infection." (PMID 30417125, 2018). "Mechanistically, immune responses to the viral infection, which involve secretion of high levels of interferons and other pro-inflammatory cytokines, induce APOL1 expression in podocytes." (PMID 40940784, 2025). "In conclusion, interference with APOL1 or APOL3 activities can affect viral infection through their influence on virus replication, but also through their involvement in antiviral signaling and the building of the immune response." (PMID 39768205, 2024). "The pathologic effects of APOL1-RA in the human kidney appear to follow a two-hit model, whereby a viral infection or inflammatory stimuli increases the expression level of APOL1 in podocytes and precipitates certain kidney diseases." (PMID 37925499, 2023). "The endogenous expression of APOL1 is induced under inflammatory conditions, such as viral infections, primarily activating the Toll-like receptor 3 (TLR3) via increased type 1 interferons, which is mimicked in vitro by incubation of cells with poly(I:C)." (PMID 34440683, 2021). "HIV and other viral infections can induce podocyte injury and FSGS with an increasing interest in the enhanced susceptibility conferred by APOL1-risk alleles." (PMID 29713631, 2018). "In many cases, viral infection may be the trigger to CG development, especially in patients harboring APOL1-HRG." (PMID 41278320, 2025). "Therefore, individuals devoid of APOL1 or APOL3, or expressing the APOL1 variants G1 or G2, may exhibit defects in resistance to viral infection, but also reduced ability to respond to pathogens in general." (PMID 39768205, 2024).
viral infection (continued). "However, the absence or inactivation of APOL1, such occurs with inaxaplin treatment, is expected to impair the induction of mitophagy under inflammatory conditions, which should aggravate the pathology of viral infection." (PMID 39451256, 2024). "Consistent with the report, we also detected that ERV_2446004 and ERV_2446045 were neighbored by APOL1, while ERV_0238545 was neighbored by IFI6; these ERVs were among the 43 pairs that were closely related to viral infections." (PMID 34009516, 2021). "Although viral infection is established as a stereotypic trigger for APOL1-FSGS, not every G1-/G2-expressing individual who encounters viral insult develops disease—additional genetic and/or environmental modifiers or “third hits” likely play a role to modify disease risk." (PMID 37461136, 2023).